DEFB4A (defensin beta 4A)
Description:
Exhibits antimicrobial activity against Gram-negative bacteria and Gram-positive bacteria, with highest activity against Gram-negative bacteria. Antimicrobial activity against P.aeruginosa seems to be salt-sensitive and is reduced with high salt concentrations greater than 25 mM. Also exhibits antimicrobial activity against the yeast C.albicans. Permeabilizes C.albicans cell membranes via targeting plasma membrane lipid phosphatidylinositol 4,5-bisphosphate (PIP2), thereby leading to cell fragmentation and cell death. Acts as a ligand for C-C chemokine receptor CCR6. Binds to CCR6 and induces chemotactic activity of CCR6-expressing cells, such as immature dendritic cells and memory T cells.
Synonyms: BD-2; hBD-2; SAP1; DEFB102; DEFB2; DEFB4; DEFB-2
Tractability: Small molecule: a structure with a bound ligand is known. Antibody: UniProt places it where antibodies can reach, with high confidence; its Gene Ontology location is reachable by antibodies, with high confidence; UniProt predicts a signal peptide or a membrane-spanning region.
Gene: Protein-coding gene on chromosome 8 (7,894,677 to 7,896,716, forward strand). Ensembl gene ENSG00000171711.
Subcellular location: Secreted
Pathways (Reactome):
Immune System: Beta defensins; Defensins
Gene Ontology:
Molecular function: CCR6 chemokine receptor binding; phosphatidylinositol-4,5-bisphosphate binding; protein binding; chemoattractant activity
Biological process: antifungal innate immune response; antimicrobial humoral immune response mediated by antimicrobial peptide; chemotaxis; defense response to bacterium; defense response to fungus; defense response to Gram-negative bacterium; defense response to Gram-positive bacterium; killing of cells of another organism; cell chemotaxis; G protein-coupled receptor signaling pathway; immune response; defense response; positive chemotaxis
Cellular component: extracellular region; Golgi lumen
Genetic constraint (gnomAD): Loss-of-function variants: 0 observed, 0.4 expected, observed/expected ratio (o/e) 0, 90% interval 0 to 1.85. That is too few expected variants to judge how well the gene tolerates losing a copy. Missense variants: 1 observed, 11.9 expected, observed/expected ratio (o/e) 0.084, 90% interval 0.029 to 0.4. Synonymous variants: 0 observed, 3.15 expected, observed/expected ratio (o/e) 0, 90% interval 0 to 0.94.
Homologues: Orthologues: chimpanzee DEFB4A (98% identical), rat Defb3 (50% identical), rat Defb4 (50% identical), mouse Defb4 (45% identical), mouse Defb3 (44% identical). Paralogues in human: DEFB4B (100% identical), DEFB109B (28% identical), DEFB109C (28% identical), DEFB109D (27% identical), DEFB130A (25% identical), DEFB130B (25% identical).
Diseases named in the same sentence as DEFB4A in open-access papers:
DEFB4A is named in the same sentence as 21 diseases in open-access papers, as found by Europe PMC text mining. Sharing a sentence is not in itself a finding about the gene and the disease. The quoted sentences say what the papers report.
psoriasis (15 papers, 2019 to 2025). An autoimmune condition characterized by red, well-delineated plaques with silvery scales that are usually on the extensor surfaces and scalp. "Fisetin treatment was also shown to decrease the expression of Akt2 mRNA and DEFB4A, a key contributor to the pathophysiology of psoriasis." (PMID 36741386, 2022). "We then analyzed the cells for markers typical for psoriasis, e.g., the expression of DEFB4A (coding for β-defensin 2), as well as the increase of the pro-inflammatory cytokines IL-6 and IL-8." (PMID 33801280, 2021). "The increased expression of DEFB4A in the skin of psoriasis patients has been described earlier and was recently confirmed to be a good biomarker of psoriasis." (PMID 33801280, 2021). "The skin lesions showed an increased expression of psoriasis-associated genes such as IL17A, IL22 and DEFB4A." (PMID 32316273, 2020). "DEFB4A is highly expressed in psoriasis plaques and is the most psoriasis-specific antimicrobial peptide." (PMID 32070069, 2020). "The number of neutrophil extracellular traps increase in psoriasis and upregulate the expression of DEFB4A." (PMID 32070069, 2020). "We identified IL-17 as the main Th17 cell derived cytokine that induced upregulation of the genes encoding NF-kappa-B inhibitor zeta (NFKBIZ) and psoriasis-associated mediators, including CCL20, IL36G, and the antimicrobial peptide human β Defensin 2 (DEFB4A)." (PMID 30972071, 2019). "In addition, some of these core NB-UVB-downregulated DEGs, such as IL36G and DEFB4A/B, were involved in IL-6 and IL-17 signaling, which are key cytokines in psoriasis pathogenesis." (PMID 36928592, 2023). "The psoriasis-like phenotype of stimulated HPKs was determined by analyzing the expression of pro-inflammatory cytokines and the expression of the psoriasis marker β-defensin 2 (DEFB4A)." (PMID 32316273, 2020). "DEFB4A has been shown to mediate the activation of CCR6 Th17 cells, further supporting its role in psoriasis." (PMID 38596682, 2024). "It induces the expression of other psoriasis signature genes, such as IL36G, S100A15, DEFB4A, S100A9, CXCL8, TNIP3 (coding TNF-α-induced-protein 3 or TNFAIP3), and LCN2 (by synergy of IL-17C with TNF-α) in keratinocytes." (PMID 36928592, 2023). "After IL-17A blockade, KC expression of IL36G, S100A8, DEFB4A, and DEFB4B in S. corneum and S. granulosum decreased in posttreatment psoriasis lesional skin compared to pretreatment psoriasis lesional skin (p < 0.05)." (PMID 37781383, 2023). "In conclusion, NB-UVB normalizes psoriatic plaques by suppressing the expression of psoriasis signature genes, such as IL36G, DEFB4A/B, S100A15, SERPINB4, KRT16, and KRT6A in, both, the PE and CE skin." (PMID 36928592, 2023). "The expression of inflammatory mediators induced by IL-17 in keratinocytes (IL36G, S100A8, DEFB4A, and DEFB4B) was increased in pretreatment psoriasis lesional skin KCs compared to control skin KCs (p < 0.05)." (PMID 37781383, 2023). "The core NB-UVB downregulated DEGs included a few psoriasis signature genes, such as IL36G, DEFB4A/B (coding human β defensin 2), S100A15, SERPINB4, KRT16, KRT6A, and DSC220." (PMID 36928592, 2023). "After systemic IL-17A blockade, the expression of those inflammatory mediators (IL36G, S100A8, DEFB4A, and DEFB4B) was decreased in posttreatment psoriasis lesional skin KCs compared to pretreatment psoriasis lesional skin KCs (p < 0.05)." (PMID 37781383, 2023). "The expression of IL-17-driven inflammatory mediators (IL36G, S100A8, DEFB4A, and DEFB4B) in suprabasal keratinocytes was correlated with psoriasis severity and was downregulated by IL-17A blockade." (PMID 37781383, 2023). "Other psoriasis-specific enriched pathways included lipid metabolism (e.g. ACOT4, S1PR3), keratinization (e.g. LCE5A, KRT5/7/16), neutrophil degranulation, and antimicrobial peptides (e.g. LTF, DEFB4A, S100A7-9)." (PMID 38433843, 2024).
psoriasis (continued). "When we compared KC transcriptome in different epidermal layers, the expression of IL-17-driven inflammatory mediators (IL36G, S100A8, DEFB4A, and DEFB4B) was localized to suprabasal layers (S. corneum, S. granulosum, and S. spinosum) in pretreatment psoriasis lesional skin." (PMID 37781383, 2023).
viral infection (3 papers, 2020 to 2024). "To test whether these protein candidates would be detectable in clinical samples, we selected four proteins (IL1Α, IL12B, DEFB4A, and CAMP) for ELISA analysis based on the following criteria: abundance, repeatability, and association with viral infection." (PMID 32867704, 2020). "Furthermore, IL1A, IL12B, DEFB4A, and CAMP, which are associated with the inflammatory response and inhibition of viral infection, were significantly more abundant in the HSV-1 epithelial keratitis patients than in the healthy control subjects." (PMID 32867704, 2020). "Several of the upregulated genes indicated a cellular response to viral infection (CXCL11, CCL8, DEFB103A, IFI6, ACOD1, and DEFB4A)." (PMID 38755665, 2024).
endothelial dysfunction (1 paper, 2020). In vascular diseases, endothelial dysfunction is a systemic pathological state of the endothelium (the inner lining of blood vessels) and can be broadly defined as an imbalance between vasodilating and vasoconstricting substances produced by (or acting on) the endothelium. "Proinflammatory cytokines from such inflamed fat also stimulates S100A7 and DEfB4A expression and can cause endothelial dysfunction in local blood vessels in part due to inadequate endothelin-1 action." (PMID 32826922, 2020).
esophageal squamous cell carcinoma (1 paper, 2020). Esophageal squamous cell carcinoma (ESCC) is a type of esophageal carcinoma (EC) that can affect any part of the esophagus, but is usually located in the upper or middle third. "Two genes, DEFB4A and PDS5B, are associated (GeneRIF) with Esophageal squamous cell carcinoma (ESCC)." (PMID 32586322, 2020).
fungal infections (1 paper, 2018). "We highlighted the beta-defensin genes (DEFB1, DEFB4A, DEFB5, DEFB6, DEFB7, DEFB10, and DEFB13) that encode host defense peptides that are critical to protection against bacterial, viral and fungal infections, and acts as an important link between innate and adaptive immune responses." (PMID 30223795, 2018).
influenza (1 paper, 2024). An acute viral infection of the respiratory tract, occurring in isolated cases, in epidemics, or in pandemics; it is caused by serologically different strains of viruses (influenzaviruses) designated A, B, and C, has a 3-day incubation period, and usually lasts for 3 to 10 days. "Among proteins related to multiple infections, 30 out of 38 were associated with influenza, including total APOE, APOE3, APOE4 (apolipoproteins), DEFB4A (an antimicrobial peptide) and RAG1 (a VDJ recombination activator)." (PMID 39143319, 2024).
Obesity (1 paper, 2022). Accumulation of substantial excess body fat. "However, DB decreased (concentration effect: P < 0.05) DEFB1 mRNA expression and tended to decrease (concentration effect: P = 0.05) DEFB4A mRNA expression in patients with obesity but not in lean individuals." (PMID 34784295, 2022).
periodontitis (1 paper, 2025). An acute or chronic inflammatory process that affects the tissues that surround and support the teeth. "Furthermore, genes encoding proteins with critical roles in immune response, such as CD207 (Langerin) and defensin Beta 4 (DEFB4A), were significantly downregulated in periodontitis-affected tissues." (PMID 41124422, 2025).
infection (10 papers, 2017 to 2025). The state of being infected such as from the introduction of a foreign agent such as serum, vaccine, antigenic substance or organism. "Among the β-defensin genes analyzed, significant changes in response to AIV infection were mainly detected in the spleen (and to some extent in the lung) of chickens, where AvBD1, 4, and 6 as well as DEFB4A were all downregulated at 3 dpi." (PMID 37358408, 2023). "On the contrary, infection was associated with a trend towards an increase in DEFB1 and DEFB103 transcript levels in adults, as well as DEFB1 and DEFB4A transcript levels in elderly subjects." (PMID 34858406, 2021). "It is plausible that altered regulation of DEFB4A following E-smoke exposure may affect response to infection." (PMID 33235237, 2020). "Some of these effectors were responsive to infection stimuli including beta-defensin (BD2, encoded by DEFB4A and DEFB4B) and elafin (encoded by PI3) as they were not present at high concentrations in the uninfected controls." (PMID 39565098, 2024). "Thus, the results above from in-depth mechanistic experiments demonstrated that MIR337-3p targeted/depressed upstream TLR4/MYD88 and STAT3 signaling and the downstream VDR antimicrobial pathways of CYP27B1/DEFB4A/CAMP, leading to an enhanced mycobacterial entry/infection and growth." (PMID 34912331, 2021).
cancer (1 paper, 2022). A tumor composed of atypical neoplastic, often pleomorphic cells that invade other tissues. "CXCL8 and LAPTM5 proteins have been reported to promote cell activity, TMEM156 and LGALS1 proteins enhance cell invasion, VIM and LGALS1 proteins induce cell migration, FABP5 and SRGN proteins activate cancer metastasis, and the DEFB4A protein regulates immunity in human cancers." (PMID 35632763, 2022).
DEFB4A also shares sentences with these, for which no sentence is quoted: asthma (1 paper); atopic dermatitis (1); keratitis (1); melanoma (1); oesophageal cancer (1); pneumonia (1); pulmonary fibrosis (1); respiratory diseases (1); skin (1); thymoma (1); tuberculosis (1).